ARSFP1 (arylsulfatase F pseudogene 1)
Synonyms: ARSFP
Gene: Transcribed unprocessed pseudogene on chromosome Y (12,252,321 to 12,258,033, reverse strand). Ensembl gene ENSG00000232226.
Diseases named in the same sentence as ARSFP1 in open-access papers:
ARSFP1 is named in the same sentence as 1 disease in open-access papers, as found by Europe PMC text mining. Sharing a sentence is not in itself a finding about the gene and the disease.
ARSFP1 shares sentences with these, for which no sentence is quoted: hearing loss (1 paper).